PRL (prolactin)
Diseases named in the same sentence as PRL in open-access papers (continued):
Sharing a sentence is not in itself a finding about the gene and the disease.
hyperprolactinemia (continued). "The cardinal features of our case were: the high prolactin suggestive of a macroadenoma, a normal MRI scan, a paradoxical rise in serum prolactin despite initiation of dopamine agonist therapy, and resolution of hyperprolactinaemia after surgical excision." (PMID 32857272, 2020). "Apparently high levels of prolactin may be due to excess circulating prolactin complexes (‘macroprolactin’) which need to be differentiated from true hyperprolactinaemia." (PMID 32857272, 2020). "Cell subpopulations that co-secrete various hormones, such as, somatomammotropes that co-secrete GH and PRL, could be the source of this hyperprolactinemia." (PMID 32958754, 2020). "Most patients with persistent hyperprolactinemia have a prolactin-secreting pituitary prolactinoma and are generally treated with dopamine agonists (bromocriptine or cabergoline) which can effectively reduce prolactin secretion and size of the lactotroph adenoma, if present." (PMID 32075620, 2020). "Elevated prolactin in a short term may promote the secretion of ketones, but long-term hyperprolactinemia can reduce the production of ketones and destroy sperm production." (PMID 32046715, 2020). "According to C. Weil, in patients with idiopathic hyperprolactinemia after treatment with bromocriptine, in 80% PRL levels are normalized, and in the absence of other causes of infertility, pregnancy occurs in 60-80%." (PMID 33426414, 2020). "Prolactin levels in patients treated with antipsychotic medication appeared to depend on patients’ gender, on the type of antipsychotic medication according to potency of inducing hyperprolactinemia, and on the duration of the psychosis." (PMID 32017792, 2020). "Switching to aripiprazole from other antipsychotics can avoid antipsychotic-induced hyperprolactinemia but may result in an abnormally low prolactin level." (PMID 33228575, 2020). "However, with non-specific symptoms such as menstrual irregularity coupled with easy access to perform PRL measurement, there will be a coincidence of such symptoms and the presence of macroprolactinemia as seen in patients with idiopathic hyperprolactinemia." (PMID 32550971, 2020). "Symptomatic hyperprolactinemia in PES is rare in general but some patients might present with symptoms related to high prolactin." (PMID 32943019, 2020). "The PRL at baseline might result from differential prolactin-elevation potencies of preswitching antipsychotics, e.g., risperidone and amisulpride that have been reported to have a higher likelihood of hyperprolactinemia." (PMID 33228575, 2020). "Nevertheless, the power of the test may be compromised due to the significantly different number of patients in each subgroup and the number of patients with hyperprolactinemia decrease with increasing basal PRL levels." (PMID 32982975, 2020). "The most common scenario is hypogonadism due to a prolactinoma, and here the pathophysiology is mediated by hyperprolactinemia itself or via interference with the inhibitory effect of dopamine on prolactin secretion, by the suppression of GnRH by excess cortisol, and/or by hyperandrogenemia." (PMID 31220230, 2019). "It has been postulated that stress-induced changes in dopamine and serotonin may affect PRL release contributing to hyperprolactinaemia in this setting." (PMID 31847209, 2019). "Hyperprolactinaemia is also seen in adenomas co-secreting GH and PRL." (PMID 31847209, 2019). "Furthermore, recent study demonstrated that treatment of hyperprolactinemia with cabergoline resulted in a cognitive enhancement in patients with prolactin-secreting pituitary adenomas." (PMID 31253144, 2019). "On the other hand, prolactin-sparing antipsychotics, such as olanzapine, do not have long-lasting D2 antagonism effects and do not cause long-term hyperprolactinemia, therefore leading to minimal loss of BMD." (PMID 31019532, 2019).
hyperprolactinemia (continued). "Hyperprolactinemia is known to suppress testosterone synthesis and male fertility through prolactin-induced hypersecretion of adrenal corticoids or by inhibiting the secretion of gonadotropin-releasing hormone through prolactin receptors on hypothalamic dopaminergic neurons." (PMID 30931169, 2019). "PRL may impact insulin resistance; patients with hyperprolactinaemia have higher insulin, HOMA-IR, and HOMA-β index levels compared with healthy controls." (PMID 31847209, 2019). "Despite the finding that lactation and nipple stimulation can increase PRL, breast examination, breast ultrasound, or mammography do not appear to cause hyperprolactinaemia." (PMID 31847209, 2019). "Hyperprolactinemia is diagnosed when blood prolactin concentration is greater than 25 ng/ml." (PMID 30627169, 2018). "In regards to hyperprolactinemia in emerging psychosis, women have been found to have higher prolactin levels, even after correcting for biological variation, which may suggest a sex-dependent stress response with prolactin, which should be further elucidated." (PMID 30627169, 2018). "A prolactinoma is the most common cause of chronic hyperprolactinemia once pregnancy, primary hypothyroidism, and drugs that raise serum prolactin (PRL) levels have been ruled out." (PMID 29768629, 2018). "With the exception of risperidone, amisulpride and molindone, which are often associated with high PRL levels, most of the AAPs elicit a poor hyperprolactinemic response or no hyperprolactinemia at all." (PMID 29768629, 2018). "For the correct identification of the etiology of hyperprolactinemia, some parameters must be taken into account: medical history, physical examination, clinical features, laboratory findings (especially PRL serum levels), and imaging studies of the pituitary and sella turcica." (PMID 29768629, 2018). "Similar inhibitory action of PRL onto sexual behaviour occurs under chronic hyperprolactinaemia." (PMID 30571750, 2018). "Additionally, there is evidence that adjunctive metformin significantly lowers prolactin levels and alleviates symptoms of hyperprolactinemia as compared to bromocriptine therapy alone." (PMID 30627169, 2018). "Some studies have reported that hyperprolactinemia is more common in RA and serum PRL levels are correlated with several disease parameters, although others could not confirm these findings." (PMID 28690611, 2017). "In addition, social drinkers had anovulatory cycles, and 3 of 5 heavy drinkers exhibited excessive levels of prolactin in the blood (i.e., hyperprolactinemia)." (PMID 28988577, 2017). "There are other causes of increased PRL level in serum such as use of various drugs, compression of the pituitary stalk, presence of macroprolactin, renal failure, cirrhosis or idiopathic hyperprolactinemia are diagnoses that may increase PRL level." (PMID 28593164, 2017). "Hyperprolactinemia in the context of reproduction and non-inflammatory pathology (prolactinoma) promotes bone loss, whereas high circulating PRL levels can be anti-inflammatory and reduce bone loss under inflammatory conditions (and present findings)." (PMID 28506283, 2017). "The mechanisms governing the effects of PRL on bone remodeling are challenging but a better understanding of them could lead to the use of hyperprolactinemia-inducing drugs as therapeutic agents in the clinic." (PMID 28506283, 2017). "The big-big prolactin was considered for a long time as a rather rare form of hyperprolactinemia." (PMID 29187947, 2017). "Its detection with most of the available immunoassays in the same way as the monomeric form of PRL may result in a false diagnosis of hyperprolactinemia." (PMID 29187947, 2017). "Hyperprolactinemia was induced by a chronic sc infusion of prolactin." (PMID 27901187, 2016).
hyperprolactinemia (continued). "In patients with NFPA, hyperprolactinemia occurs by compression of the pituitary stalk, which prevents the arrival of dopamine to the anterior pituitary, the main inhibitor of prolactin secretion, characterizing the hypothalamic-pituitary disconnection (stalk effect)." (PMID 27533614, 2016). "The presence of correlations between all domain scores and monomeric prolactin levels suggests that the degree of hyperprolactinemia, not the underlying disorder, is the main factor determining the severity of sexual dysfunction." (PMID 26902871, 2016). "Nevertheless, to account for possible prolactin pulsatility, multiple sampling (at 15- to 20-minute intervals) may be useful in confirmation of diagnosis of hyperprolactinaemia." (PMID 27716353, 2016). "Hyperprolactinemia in acromegaly patients points out to either mixt GH and PRL tumor release or pituitary stalk compression in the setting of suprasellar macroadenoma but raises also the possibility of two independent GH- and PRL-secreting adenomas." (PMID 26869991, 2016). "In women with monomeric hyperprolactinemia, sexual arousal, lubrication, orgasm, sexual satisfaction, and dyspareunia inversely correlated with total prolactin levels and prolactin concentration after polyethylene glycol precipitation (r values between −0.25, p < 0.05 and −0.41, p < 0.001)." (PMID 26902871, 2016). "It has been suggested that antipsychotic-induced hyperprolactinaemia (defined as a serum PRL >24 ng/ml for females and a level >20 ng/ml for males) could play a role in the development of reduced BMD in people with schizophrenia." (PMID 27696144, 2016). "Also, inducing decreased PRL by exogenous dopamine reduces DHEAS levels, whereas hyperprolactinemia is associated with elevated DHEAS." (PMID 26757742, 2016). "The decrease in BMD was correlated with longer treatment periods in the high-PRL group, rather than with PRL levels, suggesting that the duration of hyperprolactinaemia may have a greater impact than PRL levels themselves." (PMID 27696144, 2016). "Elevated prolactin levels (endogenous or exogenous source) as a potential trigger of IGM is supported by the hypothesis that hyperprolactinemia may contribute to increased ductal secretions, leading to damaged ductal epithelium." (PMID 27221974, 2016). "Patients with acromegaly may occasionally present with markedly elevated levels of prolactin in cases of GH- or prolactin-secreting adenomas, and hyperprolactinaemia may occur in a subset of patients with primary hypothyroidism." (PMID 27716353, 2016). "In addition, considerable experimental data and limited clinical data support the involvement of hyperprolactinemia in adenomyosis, yet prolactin is a potent cofactor for platelet aggregation." (PMID 27724926, 2016). "This study was aimed at investigating whether metformin treatment has an impact on plasma prolactin levels in bromocriptine-treated patients with hyperprolactinaemia and impaired glucose tolerance." (PMID 25239203, 2015). "Moreover, PRL levels are lower after delivery as compared to levels before conception and complete remission of hyperprolactinemia has been reported in 17–37% of women after pregnancy." (PMID 25699020, 2015). "Apart from the visual impairment, the patient also demonstrated a mild hyperprolactinaemia, which may due to the compression of the pituitary stalk or the inflmmatory process itself preventing the inhibitory regulation of PRL release by hypothalamic dopamine." (PMID 26181544, 2015). "The elevation of prolactin in this patient was modest which suggests that his hyperprolactinemia may be due to stalk effect or an inefficient macroprolactinoma." (PMID 25861507, 2015). "Some studies reported hyperprolactinemia as a possible cause of infertility, whereas the remaining studies found no statistically significant elevation of serum PRL concentration between the two groups." (PMID 26000006, 2015).
hyperprolactinemia (continued). "Elevated prolactin levels may be of particular concern for children, as hyperprolactinemia can adversely affect long-term physical and sexual development, having been associated with conditions such as amenorrhea, erectile dysfunction and osteoporosis." (PMID 26611280, 2015). "As in females, pathological hyperprolactinemia causes infertility in males, but it is not clear that there is an adaptive role for prolactin in male reproduction." (PMID 26101377, 2015). "The evidence does not support the commonly held view that dopamine agonists, which also suppress the secretion of prolactin, are more effective in patients with hyperprolactinemia (who may harbor mixed GH- and prolactin-secreting pituitary tumors)." (PMID 24166706, 2014). "Clinical equivalence for prolactin lowering effects of Vitex agnus-castus (Agnucaston® 40 mg per day) and the pharmaceutical Bromocriptine (Parlodel® 5 mg per day) was found in one study including 40 women with hyperprolactinaemia." (PMID 25524718, 2014). "In other studies using peripheral blood mononuclear cells (PBMC) of patients with hyperprolactinemia revealed that exogenous recombinant human prolactin (rhPRL), as well as autologous shPRL from inactivated serum, significantly restricted intracellular growth of Toxoplasma in these cultures." (PMID 25346725, 2014). "Moreover, despite the persistent hyperprolactinaemia produced in I rats, the incidence of tumors was similar to the other groups, suggesting a null impact of serum PRL levels on mammary carcinogenesis." (PMID 25136563, 2014). "Demographic and clinical variables in normal prolactin group and hyperprolactinemia group." (PMID 24312671, 2013). "However, there is evidence for overlapping clinical features among subjects with hyperprolactinemia due to monomeric or “big big” PRL isoform." (PMID 23401806, 2013). "The majority of clinical adverse effects of hyperprolactinaemia involves the reproductive system and is attributed to prolactin direct relation with several tissues as well as indirect suppression of pulsatile gonadotropin secretion, leading to gonadal dysfunction." (PMID 24490071, 2013). "The major circulating isoform of PRL is a 23 kDa single polypeptide chain (monomeric PRL), which comprises up to 80% of the total PRL in serum from normal subjects and the majority of patients with hyperprolactinemia (HPRL)." (PMID 24194758, 2013). "A similar PRL effect may explain the reduced numbers of pro-B cells observed during hyperprolactinemia." (PMID 24454471, 2013). "However, the mean PRL level was 28.93 ng/ml for five of the six patients with hyperprolactinemia in the present study; the sixth one had marked hyperprolactinemia (163.5 ng/ml)." (PMID 24312671, 2013). "Prolactin levels have also been found to be positively correlated with reported ejaculatory latency (from severe premature ejaculation to anejaculation), after excluding men with pathological hyperprolactinaemia and adjusting for SSRI use." (PMID 23606840, 2013). "This review aims to summarize the effects of antipsychotic agents on prolactin levels and menstruation and investigate the frequency of hyperprolactinaemia and menstrual abnormalities that affect female patients, depending on the selected antipsychotic therapy." (PMID 24490071, 2013). "Hyperprolactinaemia in mice susceptible to lupus accelerated the disease and increased the absolute numbers of T1 and T3 B cells but not mature B cells, suggesting that PRL participates in the early stages of splenic B cell development." (PMID 22404893, 2012). "However, most antipsychotics block dopamine-D2 receptors, attenuating the inhibitory effect of dopamine on prolactin release from the pituitary gland and resulting in hyperprolactinemia." (PMID 22348381, 2012). "Thereby, raised serum PRL level and hyperprolactinemia appear." (PMID 22527578, 2012).
hyperprolactinemia (continued). "Despite that quetiapine is considered to be a prolactin-sparing atypical antipsychotic, hyperprolactinemia with related side effects may rarely be encountered in susceptible individuals." (PMID 21267374, 2010). "But again, normal serum prolactin with all clinical features of hyperprolactinemia might question the diagnosis and further management." (PMID 21209758, 2010). "In terms of hyperprolactinemia induced sexual dysfunction, our result, the positive correlation between prolactin and the activity of cognitive component for sexual arousal finding, may look like an inconsistent finding." (PMID 20046395, 2009). "Risperidone-treated patients are more likely to undergo prolactin assessment regardless of prior PPAEs, and more likely to undergo MRI/CT in association with hyperprolactinemia or PPAEs." (PMID 19210771, 2009). "For example, in many instances, potentially prolactin-related symptoms may not have been reported on medical claims, particularly if they were first noted immediately prior to a prolactin test and diagnosis of hyperprolactinemia." (PMID 19210771, 2009). "Prolactin is involved in the differentiation and development of normal breast tissue, and there have been reports of bilateral breast cancer in patients with pituitary tumor, especially when accompanied by hyperprolactinemia." (PMID 17543123, 2007). "Apart from stimulating milk production, elevated PRL levels (termed hyperprolactinemia) may affect fertility." (PMID 23675050, 2007). "Further, this randomized, placebo-controlled trial of r-hPRL administration for seven days isolated the effect of prolactin on bone from the effect of hypoestrogenemia and changes in the hormones regulating calcium homeostasis that can accompany hyperprolactinemia and lactation." (PMID 17650319, 2007). "Similarly, women with pathological hyperprolactinemia and amenorrhea exhibit lower radial bone mineral content than amenorrheic women with normal prolactin levels." (PMID 17650319, 2007). "However, when patients were grouped according to their prolactin level, the score for short-term memory was 0.98 ± 0.01 in patients with normoprolactinemia, 0.75 ± 0.25 in patients with hyperprolactinemia and 0.63 ± 0.51 in patients with hypoprolactinemia (p = 0.005)." (PMID 39361237, 2025). "Contralateral PRL suppression may also occur due to local hyperprolactinemia." (PMID 41287677, 2025). "Hyperprolactinemia in a patient with a pituitary mass can be the result of tumor production but also occurs in patients with masses that do not produce PRL but interrupt the tonic hypothalamic inhibition of PRL secretion by dopamine, including even inflammatory disorders." (PMID 40718390, 2025). "A brain MRI is performed to rule out a PRL-secreting tumor, which may be causing central hyperprolactinemia." (PMID 39974504, 2025). "In addition, it is interesting to point out that the rate of postsurgical hyperprolactinemia was five times greater in the group of GH&PRL-PAs than in GH-PAs and this may be an indicator of tumoral persistence in cosecreting tumors." (PMID 40590355, 2025). "In a case series, we observed hyperprolactinemia-associated unilateral headache including migraine to resolve in a rapid and pronounced manner after dopamine-agonist treatment irrespective of adenoma size and prolactin lowering." (PMID 40168298, 2025). "Finally, PRL has been recognized to influence bone density; in particular, postmenopausal women with hyperprolactinemia show multiple effects on bone metabolism, affecting both bone mass and density, which in turn is associated with a high risk of osteoporosis." (PMID 40806464, 2025). "Hyperprolactinemia, seen in 13.4% of cases in this systematic review, may result from pituitary stalk compression and dopamine insufficiency or fungal glucans’ stimulation of prolactin release." (PMID 40137270, 2025).